ATP1B4 (ATPase Na+/K+ transporting family member beta 4)
Description:
May act as a transcriptional coregulator during muscle development through its interaction with SNW1. Has lost its ancestral function as a Na,K-ATPase beta-subunit.
Tractability: Antibody: its Gene Ontology location is reachable by antibodies, with high confidence; UniProt predicts a signal peptide or a membrane-spanning region.
Gene: Protein-coding gene on chromosome X (120,362,085 to 120,383,249, forward strand). Ensembl gene ENSG00000101892.
Subcellular location: Nucleus inner membrane
Pathways (Reactome):
Signal Transduction: Downregulation of SMAD2/3:SMAD4 transcriptional activity
Gene Ontology:
Molecular function: protein binding; transmembrane transporter activity
Biological process: regulation of DNA-templated transcription; transmembrane transport; potassium ion transport; sodium ion transport
Cellular component: nuclear inner membrane; nuclear envelope; plasma membrane; nucleus; sodium:potassium-exchanging ATPase complex
Homologues: Orthologues: chimpanzee ATP1B4 (99% identical), macaque ATP1B4 (97% identical), dog ATP1B4 (93% identical), pig ATP1B4 (92% identical), rabbit ATP1B4 (91% identical), guinea pig ATP1B4 (89% identical), mouse Atp1b4 (88% identical), rat Atp1b4 (88% identical), tropical clawed frog atp1b4 (43% identical), zebrafish atp1b4 (39% identical). Paralogues in human: ATP1B2 (32% identical), ATP1B3 (28% identical), ATP4B (28% identical), ATP1B1 (27% identical).
Diseases named in the same sentence as ATP1B4 in open-access papers:
ATP1B4 is named in the same sentence as 6 diseases in open-access papers, as found by Europe PMC text mining. Sharing a sentence is not in itself a finding about the gene and the disease. The quoted sentences say what the papers report.
endometriosis (1 paper, 2019). The growth of functional endometrial tissue in anatomic sites outside the uterine body. "Our results are in line with previous studies that showed differing expression of the protein ATPase Na+/K+ Transporting Family Member Beta 4 (ATP1B4) between patients with and without endometriosis, in favor of a decrease of the hydrolysis of ATP in the endometriosis patients." (PMID 31698766, 2019).
Incisional hernia (1 paper, 2025). An abdominal hernia that occurs at a site of weakness in the abdominal wall resulting from an incompletely-healed surgical wound. "Although BetaM expression gradually declines after birth and becomes nearly undetectable in adult mouse skeletal muscle, the activation of ATP1B4 was detected in the superficial fascia tissue of patients with incisional hernias, along with the activation of inflammatory pathways." (PMID 40724605, 2025).
Obesity (1 paper, 2025). Accumulation of substantial excess body fat. "This demonstrates that bypassing the co-option of Atp1b4 potentially reduces susceptibility to obesity." (PMID 40724605, 2025).
ATP1B4 also shares sentences with these, for which no sentence is quoted: breast tumors (1 paper); cancer (1); cardiovascular disease (1).